CDC25B (cell division cycle 25B)
Diseases named in the same sentence as CDC25B in open-access papers (continued):
Sharing a sentence is not in itself a finding about the gene and the disease.
non-small cell lung carcinoma (9 papers, 2002 to 2025). A group of at least three distinct histological types of lung cancer, including non-small cell squamous cell carcinoma, adenocarcinoma, and large cell carcinoma. "Research has shown that several downstream targets of FOXM1, including survivin, cyclin B1, S-Phase Kinase-Associated Protein 2, and CDC25B, were significantly upregulated in non-small-cell lung cancer cells treated with gefitinib." (PMID 37242455, 2023). "High expression of CDC25B exhibits a positive correlation with poor prognosis in esophageal squamous cell carcinoma, pancreatic ductal adenocarcinoma, and non-small cell lung carcinoma." (PMID 40216745, 2025). "Previous studies have demonstrated that cdc25B overexpression reflects a worse clinical outcome in patients with colorectal, ovarian, and non-small-cell lung carcinomas." (PMID 12085185, 2002). "CDK7 inhibitors can improve the efficacy of anti-PD-1 therapy for non-small cell lung cancer (NSCLC).Therefore, we further investigated the relationship between CDC25B and the TME and immune checkpoints." (PMID 39371450, 2024).
esophageal squamous cell carcinoma (8 papers, 2001 to 2022). Esophageal squamous cell carcinoma (ESCC) is a type of esophageal carcinoma (EC) that can affect any part of the esophagus, but is usually located in the upper or middle third. "Some of the differentially-expressed genes reported in GCA were also dysregulated in a similar pattern as esophageal squamous cell carcinomas (ESCC) examined from this same high-risk population, such as CDC25B and COL1A2." (PMID 23717493, 2013). "Autoantibodies against CDC25B also indicated poor prognosis in advanced esophageal squamous cell carcinoma (ESCC) patients." (PMID 36341384, 2022). "CDC25B mRNA levels are significantly elevated in esophageal squamous cell carcinoma tissues, and higher levels of CDC25B are present in sera from tumors than in sera from healthy control subjects." (PMID 35743699, 2022). "In addition, FAM83A-AS1 promoted the progression of esophageal squamous cell carcinoma (ESCC) by regulating the miR-214/CDC25B axis." (PMID 36605426, 2022). "In esophageal cell squamous carcinoma, FAM83A-AS1 downregulation regulates the miR-214/CDC25B axis to suppress tumor cell growth, invasion and migration." (PMID 34488540, 2021).
melanoma (7 papers, 2013 to 2025). A malignant, usually aggressive tumor composed of atypical, neoplastic melanocytes. "Naphthylphenylketone and naphthylphenylamine derivatives that function as CDC25B phosphatase inhibitors potently inhibited cell proliferation and colony formation, inducing G2/M-phase cell-cycle arrest in melanoma cell lines." (PMID 35743699, 2022). "Consistently with the cell proliferation results, the SQ22536 pretreatment abrogated the carvone-induced phosphorylation of Cdc25B and CDK1 in B16F10 melanoma cells." (PMID 33171851, 2020). "Consistent with other studies, in the present study carvone stimulated the cAMP pathway and increased the phosphorylation of Cdc25B and CDK1 via cAMP in conjunction with decreased proliferation of melanoma cells." (PMID 33171851, 2020). "Our analyses pointed out a down modulation of cell cycle regulators cyclin B1, cdc25B, and CDK4, which certainly contributes to the inhibition of cell proliferation exerted by D6 on melanoma cells." (PMID 23642048, 2013). "As a result, high expression of CDC25A/C, but not CDC25B, predicted short survival of melanoma patients in OS, DSS, or PFS." (PMID 40216745, 2025). "Notably, accumulating evidence suggests that cAMP signaling can strongly suppress the activity of CDK1 mainly owing to the phosphorylation of Cdc25B and subsequent phosphorylation of CDK1 in various cell types, including melanoma cells." (PMID 33171851, 2020). "Further analysis showed that CDC25A, not CDC25B or CDC25C, plays a more dominant role in melanoma development." (PMID 40216745, 2025). "Taken together, our studies demonstrate that, within the CDC25 family, CDC25A, rather than CDC25B or CDC25C, plays a more dominant role in melanoma progression." (PMID 40216745, 2025).
hepatocellular carcinoma (6 papers, 2008 to 2024). A malignant tumor that arises from hepatocytes. "CDC25B has been shown to be overexpressed in patient populations with hepatocellular carcinoma, and this is frequently associated with poor prognosis." (PMID 31731549, 2019). "Studies have suggested its carcinogenic potential in various cancers, but the role of CDC25B in the development of hepatocellular carcinoma (HCC) remains poorly understood." (PMID 39371450, 2024). "Unfortunately, correlation analysis between MCM7 and CDC25B expression in hepatocellular carcinoma cell lines or clinical hepatocellular carcinoma tissues was not performed in this study to further validate the important role of MCM7 in the CDC25B-CDK1 axis." (PMID 39371450, 2024). "In an earlier gene expression study of hepatocellular carcinoma, CDC25B was upregulated in tumor compared to non-tumor samples." (PMID 18269767, 2008). "We used quantitative real-time PCR assays to validate the observed upregulation of CDC25B in hepatocellular carcinoma using 24 pairs of HCC tissues and adjacent non-tumor tissues." (PMID 18269767, 2008). "Using gene expression profiling, we previously identified CDC25B to be significantly highly expressed in hepatocellular carcinoma (HCC) compared to non-tumor liver." (PMID 18269767, 2008). "In vitro, the HCC-LM3 cell line with knockdown of CDC25B had decreased proliferation, suggesting that high expression of CDC25B enhances the proliferation of hepatocellular carcinoma cells in vitro and tumorigenicity in vivo." (PMID 39371450, 2024). "However, there are some shortcomings in our study, such as the fact that we did not validate the function of CDC25B in a variety of hepatocellular carcinoma cell lines, and we did not validate the results of the biosignature analysis by performing experiments on the signaling pathway mechanisms." (PMID 39371450, 2024).
bladder cancer (5 papers, 2014 to 2024). "Overexpression of Cdc25B was found in many malignancies including bladder, gastric, endometrial, and renal cell cancers, and cdc25B overexpression was associated with a higher recurrence rate and a poorer prognosis in bladder cancer." (PMID 27626805, 2016). "CircZNF609 contributes to bladder cancer progression and decreases cisplatin sensitivity through the miR‐1200/CDC25B axis." (PMID 39502735, 2024).
cervical cancer (5 papers, 2011 to 2025). A primary or metastatic malignant neoplasm involving the cervix. "The IER5 gene is sensitive to radiotherapy in cervical cancer, and Cdc25B is an important cyclical regulatory protein of the G2/M transition in HeLa cells, which is critical to our understanding of cell proliferation and apoptosis." (PMID 40852688, 2025). "Despite this limitation, our findings highlight the role of IER5 in modulating Cdc25B expression postirradiation, suggesting a potential therapeutic strategy for cervical cancer." (PMID 40852688, 2025). "METTL3 can also affect the translation of CDC25B mRNA which will accelerate the process of cell cycle and promote the growth of cervical cancer cells." (PMID 38343637, 2024). "Taken together, METTL3 and CDC25B expression are upregulated in human cervical cancer samples and the expression of CDC25B was related to that of METTL3." (PMID 35637959, 2022). "If this regulatory mechanism is confirmed and further investigated, Cdc25B may become an important target for cervical cancer treatment and lead to optimized radiotherapy for this disease." (PMID 40852688, 2025). "The expression of METTL3 is correlated with the expression of CDC25B in cervix cancer." (PMID 35637959, 2022). "Furthermore, using an immunochemistry assay, we showed that the protein expression of METTL3 was related to CDC25B expression in cervical cancer specimens." (PMID 35637959, 2022). "Clinical data analysis showed that METTL3 and CDC25B were highly expressed in cervical cancer." (PMID 35637959, 2022). "Contrarily, mRNA m6A modification on oncogenic CDC25B in the M phase accelerates the translation of CDC25B mRNA through YTHDF1, leading to cell cycle progression and tumorigenicity in cervical cancer." (PMID 39087001, 2024).
colon carcinoma (5 papers, 2019 to 2025). "Both CDC25B and COX-2 can be expressed in high risk polyps that may progress to carcinomas, so we evaluated vaccination in two spontaneous tumor models for disease prophylaxis; AOM induced colon cancer and intestinal polyp formation in APC Min mice." (PMID 34526999, 2021). "Mice immunized with CDC25B (mean, 1.1 ± 1.4 tumors) or COX2 peptides (mean, 1.4 ± 1.8 tumors) developed significantly fewer colon tumors as compared to the control (mean, 6.3 ± 2.8 tumors p<0.0001 for all)." (PMID 34526999, 2021). "Besides, sulforaphene treatment was also demonstrated to induce G2/M phase cell cycle arrest and apoptosis of colon cancer cells, concomitant with phosphorylation of CDK1 and CDC25B at inhibitory sites." (PMID 31889894, 2019).
lung carcinoma (5 papers, 2017 to 2025). "CDC25B expression could be induced through HER2 signal transduction in human lung cancer cells." (PMID 28754978, 2017). "Interestingly, we found that CDC25B expression did not appear to have an impact on the overall survival of lung cancer (LUNG) patients." (PMID 33745968, 2021).
pancreatic cancer (5 papers, 2007 to 2025). "To extend this observation, we evaluated CDC25B expression in three commonly used pancreatic cancer cell lines: Panc1, BxPC3, and MIA PaCa-2." (PMID 39534870, 2024). "We used two models and three pancreatic cancer cell lines with contrasting levels of CDC25B to compare the efficacy of the BET inhibitor JQ1, which inhibits the expression of CDC25B, or of gemcitabine, a standard of care for this tumor type." (PMID 39534870, 2024). "The CDC25B inhibitors were reported to inhibit pancreatic cancer cell growth by blocking G2/M phase transition." (PMID 34366863, 2021). "We also wanted to determine if CDC25B levels reflect gemcitabine sensitivity since gemcitabine-based combination chemotherapy is a current standard of care for pancreatic cancer, and we have reported that a BETi + gemcitabine is synergistic in vitro in parent pancreatic cancer cell lines." (PMID 39534870, 2024). "CDC25B also contributes to tumor initiation and progression, but no connection between CDC25B levels and drug sensitivity in pancreatic cancer has been reported." (PMID 39534870, 2024).
pancreatic ductal adenocarcinoma (5 papers, 2021 to 2024). An infiltrating adenocarcinoma that arises from the epithelial cells of the pancreas. "It has been reported that overexpression of CDC25B is associated with pancreatic ductal adenocarcinoma and that its inhibitor prevents PC cell growth by blocking the G2/M phase transition via the inhibition of cdc2 dephosphorylation." (PMID 35547358, 2022). "CDC25B was recognized as a target of miRNA-148a which may regulate pancreatic ductal adenocarcinoma development." (PMID 33925358, 2021).
esophageal cancer (4 papers, 2014 to 2024). A primary or metastatic malignant neoplasm involving the esophagus. "Interestingly, overexpression of CDC25B is associated with sensitivity to radiation in human esophageal cancers." (PMID 39534870, 2024). "In contrast, overexpression of CDC25B in esophageal cancer models correlates with sensitivity to radiation." (PMID 39534870, 2024). "For example, overexpression of CDC25B was shown to increase apoptosis after radiation in TE8 esophageal cancer cells; yet in skin squamous cell carcinoma cell, overexpression of CDC25B appeared to inhibit apoptosis." (PMID 33745968, 2021).
prostate tumors (4 papers, 2008 to 2025). "With obvious growth-promoting properties, CDC25B over-expression has been demonstrated in a number of cancers including head, neck, gastric, ovarian, esophageal and prostate tumours, as well as non Hodgkin’s lymphoma." (PMID 19259415, 2008). "Furthermore, CDC25B, a cell cycle phosphatase frequently overexpressed in high-grade prostate tumors, has been shown to act as a co-activator of the androgen receptor (AR), thereby promoting AR-mediated transcription even under androgen-deprived conditions." (PMID 40491606, 2025). "Expression of SPDEF reduced the tumor burden, decreased the number of Ki67 and PH3-positive cells, and reduced mRNA levels of proliferation-specific genes Cdc25b, Cyclin B1, Cyclin A2, PLK1, CKS1, Aurora B and Topo2 alpha in the prostate tumors." (PMID 25254494, 2014).
squamous cell carcinoma (4 papers, 2001 to 2023). A carcinoma arising from squamous epithelial cells. "In another study, CDC25B was more frequently found in patients with deeper tumor invasion and lymph node metastasis in squamous cell carcinomas of the esophagus." (PMID 18269767, 2008). "CDC25B is significantly upregulated in squamous cell carcinoma (SCC)." (PMID 38077434, 2023). "CDC25A but not CDC25B may be a new prognostic factor for squamous cell carcinoma of the oesophagus." (PMID 11487274, 2001).
clear cell renal cell carcinoma (3 papers, 2020 to 2025). "We examined the expression of mitogen‐activated protein kinase 14 (MAPK14) and cell division cycle 25B (CDC25B) in clear cell renal cell carcinoma (ccRCC) and healthy tissue using the cancer genome atlas database and clinical samples." (PMID 31856414, 2020).
prostate carcinoma (3 papers, 2013 to 2024). A carcinoma that arises from epithelial cells of the prostate gland. "Other studies in the literature document CDC25B overexpression in multiple tumor types, including pancreatic, gastric, esophageal, and prostate cancers." (PMID 39534870, 2024).
triple-negative breast carcinoma (3 papers, 2019 to 2025). An invasive breast carcinoma which is negative for expression of estrogen receptor (ER), progesterone receptor (PR), and human epidermal growth factor receptor 2 (HER2). "We further demonstrated that knockdown of the C subunit abolished the association of the B56δ subunit with CDC25B in triple negative breast cancer cells using anti-CDC25B antibody for IP or anti-B56δ antibody for reciprocal IP." (PMID 33385163, 2020). "CDC25B gene expression is associated with metformin anticancer response in triple negative breast cancer through its regulation of AMPK via PP2A." (PMID 33385163, 2020). "Since glucose concentration was found to influence metformin sensitivity in previous studies, we also tested CDC25B knockdown under low glucose condition and observed a similar resistance effect to metformin in triple negative breast cancer cells." (PMID 33385163, 2020). "Using immunoprecipitation in triple negative breast cancer cells treated with LB100, a PP2A inhibitor, we demonstrated that LB100 significantly reduced the association between PP2A and CDC25B." (PMID 33385163, 2020). "Moreover, we demonstrated endogenous association between CDC25B and PP2A in multiple triple negative breast cancer cell lines." (PMID 33385163, 2020). "In triple-negative breast cancer models, KLT effectively blocked cell cycle progression at the G2/M phase by downregulating CDK1, CDK2, and CHEK1, inhibiting CDC25A, CDC25B, MELK, and AURKA activity, suppressing mitosis, and inducing apoptosis." (PMID 41164166, 2025). "In this study, we demonstrate that CDC25B can regulate AMPK activation through its interaction with PP2A, and block PP2A access to AMPK, resulting in increased AMPK phosphorylation in triple negative breast cancer." (PMID 33385163, 2020). "Strikingly, knockdown of CDC25B conferred resistance to metformin in triple negative breast cancer cells compared to negative siRNA transfected cells." (PMID 33385163, 2020). "Furthermore, CDC25B over-expression can activate AKT, and the co-inhibition of AKT and CDC25 has synergistic effects in the suppression of the growth of triple-negative breast cancer cells." (PMID 31024841, 2019).
acute myeloid leukemia (2 papers, 2011 to 2025). Acute myeloid leukemia (AML) is a group of neoplasms arising from precursor cells committed to the myeloid cell-line differentiation. "It has been reported that inhibition of cell proliferation in AML cells is associated with a decrease in the expression of the Cdc25B phosphatase, and that this phosphatase participates in G2/M checkpoint recovery and its expression is upregulated in acute myeloid leukemia cells." (PMID 22132193, 2011). "IER5 can competitively bind the Cdc25B promoter, inhibiting the interaction between the transcription factor NF-YB and Cdc25B, thereby inhibiting Cdc25B transcription and reducing Cdc25B expression in acute myeloid leukemia." (PMID 40852688, 2025).
cataract (2 papers, 2023 to 2025). Partial or complete opacity of the crystalline lens of one or both eyes that decreases visual acuity and eventually results in blindness. "Genetic variations of CDC25B can lead to defects in neurogenesis and even result in conditions such as cataracts, dilated cardiomyopathy, and multiple endocrine syndromes." (PMID 39753851, 2025). "Furthermore, a case with homozygous deletion mutation of CDC25B in human also does not prevent live birth (with development of clinical defects including cataracts, dilated cardiomyopathy, and multiple endocrinopathies)." (PMID 36717077, 2023).
head and neck squamous cell carcinoma (2 papers, 2022 to 2024). A squamous cell carcinoma that arises from any of the following anatomic sites: lip and oral cavity, nasal cavity, paranasal sinuses, pharynx, larynx, and salivary glands. "METTL3-mediated m6A modification of CDC25B is upregulated in head and neck squamous cell carcinoma (HNSCC), and promotes HNSCC malignant characteristics, including cell proliferation, migration, and invasion, as well as angiogenesis." (PMID 39691597, 2024).
lymph node metastasis (2 papers, 2008 to 2010). "Moreover, overexpression of CDC25B was also more frequently found in patients with deep tumor invasion and lymph node metastasis than in patients with early stage disease." (PMID 20813067, 2010).
non-Hodgkin lymphoma (2 papers, 2008). Distinct from Hodgkin lymphoma both morphologically and biologically, non-Hodgkin lymphoma (NHL) is characterized by the absence of Reed-Sternberg cells, can occur at any age, and usually presents as a localized or generalized lymphadenopathy associated with fever and weight loss. "CDC25B over-expression was found to be significantly associated with a high proliferative activity of human non-hodgkin's lymphomas, and to enhance the proliferation of mammary epithelial cells in transgenic mice over-expressing human CDC25B." (PMID 18269767, 2008).